CD4 (CD4 molecule)
Diseases named in the same sentence as CD4 in open-access papers (continued):
Sharing a sentence is not in itself a finding about the gene and the disease.
HIV-1 infection (continued). "The TZM-bl cells are of epithelial origin, and the acute T cell leukemia (ATCL) derived Jurkat T cells, like primary human CD4+ T cells, are suspension cells with expression of co-receptor CXCR4 and CCR5 on cell surface, which can be a perfect option for HIV-1 infection study." (PMID 28904745, 2017). "Given that the French 2013 guidelines for ART of HIV-1 infection in adults recommend that ART should be initiated in any HIV-positive person, whatever his/her CD4 T cell count, even when >500/mm3, we first considered a prevention intervention strategy based on immediate ART introduction." (PMID 28222757, 2017). "The same was true for CD4+ Jurkat cells, which were electroporated to express PHF13, such that in BFP-positive cells, which overexpressed PHF13, HIV-1 infection was roughly twofold more efficient when compared with Jurkat cells electroporated with a BFP-only control plasmid." (PMID 29021215, 2017). "Since microbial exposure triggered significant transcriptome changes, we next investigated if HIV-1 infection altered the same gene sets/pathways in microbe-exposed versus non-microbe exposed LP CD4+ T cells." (PMID 28241075, 2017). "The proportion of the splenic CD4+ T cells (CD3+ CD8− cells) of infected mice was significantly lower than that of uninfected mice, and particularly, CD25+ activated CD4+ T cells were severely depleted by HIV-1 infection (P = 0.0039 versus mock infection)." (PMID 28475648, 2017). "Like current experimental approaches, our modeling study fails to provide direct evidence that CD8+ T cells control HIV-1 infection by the killing of infected CD4+ T cells." (PMID 27226367, 2016). "In Jurkat and primary CD4+ T-cells, HIV-1 infection did not significantly affect the percentages of total m6A peaks mapped to the human genome in the 5′ UTR, coding DNA sequence (CDS), 3′ UTR and noncoding regions." (PMID 27371828, 2016). "Because 0.5–5 g/L AAT inhibits HIV-1 infection without affecting the viability of CD4+ T cells and this concentration is within the range found in the human body, 0.5 g/L AAT was used in the remainder of the study." (PMID 27473095, 2016). "The majority of HAMB increased HIV-1 infection and depletion of LP CD4 T cells, but gram-negative HAMB enhanced CD4 T cell infection to a greater degree than gram-positive HAMB." (PMID 26762145, 2016). "The activities of respiratory burst enzymes, which were higher in HIV-1 negative female subjects, were significantly decreased and to equal those of the male counterparts in HIV-1 infection independent of the CD4+ cell counts." (PMID 29083382, 2016). "More recently, Nef-induced exosome-associated ADAM17 (ADAM metallopeptidase domain 17) had rendered resting CD4+ T cells permissive to HIV-1 infection, whereas ADAM17 along with TNF-α has been known to synergistically activate the latent HIV-1 in primary CD4+ T lymphocytes and macrophages." (PMID 26981123, 2016). "We used MDMs and CD4+ T cells derived from ART-treated HIV-1-infected individuals and infected these cells ex vivo with the individuals’ autologous HIV-1 isolated during the acute phase of their HIV-1 infection." (PMID 27067385, 2016). "Two species that induced lower levels of HIV-1 infection, B. luti and B. infantis, also did not significantly enhance CD4 T cell depletion." (PMID 26762145, 2016). "As an alternative mechanism, AAT might directly interact with CD4, CCR5 or CXCR4, or other known HIV-1 infection-related proteins on CD4+ T cells to interfere with the interaction between HIV-1 particles and host cells." (PMID 27473095, 2016). "To evaluate the ability of C34-conjugated coreceptors to protect CD4 T cells in vivo, we employed the NSG mouse model that has been used extensively to evaluate the ability of a wide range of antiviral agents to protect T cells from HIV-1 infection in vivo." (PMID 27855210, 2016).
HIV-1 infection (continued). "Jurkat cells infected with HIV-1 and incubated with pH1N1 for another three days, had higher levels of HIV-1 RNA relative to cell with HIV-1 infection alone, suggesting that pH1N1 infection increases HIV-1 replication in co-infected cells in Jurkat cells and in CD4+ T cells." (PMID 26848681, 2016). "While HIV-1 infection specifically leads to CD4+ T-cell depletion, we do not model CD4+ T-cells separately from CD8+ T-cells." (PMID 27285483, 2016). "We found, however, that the viability of Jurkat cells and activated CD4+ T-lymphocytes either before or after HIV-1 infection was not influenced by CIB1 and CIB2 knockdown." (PMID 27489023, 2016). "Furthermore, this is in accordance with the fact that the immune CD4+ and CD8+ T-cell responses were different at distinct stages after HIV-1 infection." (PMID 27171002, 2016). "Primary CD4 T cells expressing C34-conjugated coreceptors, particularly C34-CXCR4, were resistant to HIV-1 in vitro and in vivo in NOD/SCID IL-2Rγnull (NSG) mice, as seen by expansion of these cells during HIV-1 infection." (PMID 27855210, 2016). "Therefore, taken altogether, it seems unlikely that healthy adults have a preponderance of pre-existing, activated, and resident CCR5+CD4+ T cells in the GALT, prior to HIV-1 infection." (PMID 27822211, 2016). "In addition to TRECS, we longitudinally measured the percentages of CD4+ and CD8+ cells in the T-cell pool, as well as the percentage of naive and memory cells in the CD4+ and CD8+ T-cell pools during untreated HIV-1 infection." (PMID 27010200, 2016). "Progressively increased expression of PD-1 on both CD4+ and CD8+ T-cell subsets have been shown by longitudinal studies of untreated HIV-1 infection, and could likely be a component of failed CD4+ T-cell regeneration." (PMID 27525551, 2016). "During the clinical course of HIV-1 infection, latently HIV-1 infected provirus is present in the long-lived CD4+ T memory cells that play a role as a steady source of infectious viral particles after interruption of treatment and as a major obstacle to HIV-1 eradication." (PMID 27527606, 2016). "Resting, non-proliferating CD4 T cells are prime targets of HIV-1 infection and latently infected resting CD4 T cells are the major barrier to HIV cure." (PMID 26728316, 2016). "A large variety of phenotypic dysfunctions occurring in both CD4+ and CD8+ T cells has been associated with HIV-1 infection, affecting both HIV-1-specific and non-HIV-1-specific T cells." (PMID 27281071, 2016). "Although all HAMB increased HIV-1 infection and depletion of LP CD4 T cells to some degree, gram-negative HAMB appeared to enhance infection and depletion greater than gram-positive HAMB." (PMID 26762145, 2016). "In parallel, cell free HIV-1 infection of CD4+ T cells was performed in the presence or absence of VRC01, NIH45–46 G54W or sCD4." (PMID 25760631, 2015). "The combination treatment of the five anti-HIV-1 miRNAs inhibitors were more effective in substantially increasing the HIV-1 infection compared to the individual inhibitors in resting CD4+T cells, but not in activated CD4+T cells." (PMID 26483757, 2015). "Besides the major cell surface receptor CD4, syndecans and HSPG are playing an important role for virus attachment and therefore strongly influence HIV-1 infection." (PMID 25785610, 2015). "These include one round HIV-1 infection, latently infected Jurkat (lymphoblastoid T cells), THP (monocytes) cell lines, chronically infected CEM T cells (ACH-2) and primary CD4+ T cells within the pool of infected PBMCs treated with IL-7 to transfer them to quiescent phase." (PMID 26178009, 2015). "We observed a decrease in the frequency of CD25+CD69+CD4+ T cells after HIV-1 infection when compared with non-infected cells." (PMID 25875202, 2015). "To confirm that HIV-1 infection for 3 days did not contribute to the upregulation of PD-1 on CD4+ T cells, we sorted LPL cells from uninfected HIV-1 humanized DRAG mice using a BD FACS Aria cell sorter." (PMID 26034905, 2015).
HIV-1 infection (continued). "However, at high concentrations, it can directly compete with WT-CCR5 to interact with CD4 and CCR5 on target cells to block HIV-1 infection." (PMID 26154172, 2015). "After accounting for these factors, neither HIV-1 infection nor CD4+ cell counts predicted PPF, hepatosplenomegaly, measurements of the liver or spleen." (PMID 25948238, 2015). "Several interactions between HIV-1 and cellular miRNAs have been described, suggesting that altered miRNA profile expression could contribute to the pathogenesis of HIV-1 infection and HIV-1 latency in primary CD4+ T lymphocytes." (PMID 25808800, 2015). "SAMHD1 is expressed at similar levels in MDMs, resting CD4+ T cells and in activated CD4+ T cells, but does not block HIV-1 infection in the latter." (PMID 24782834, 2014). "HIV-1 infection significantly induced CD4+ T-cell intrinsic Caspase-1 activity, whereas Caspase-1 inhibition, but not Caspase-3 inhibition, significantly blocked CD4+ T cell depletion." (PMID 24495380, 2014). "We conclude that pDC play two opposing roles during HIV-1 infection and pathogenesis: they produce IFN-I to inhibit HIV-1 replication, but enhance HIV-1 pathogenesis by promoting cell death of human leukocytes including human CD4 and CD8 T cells." (PMID 25077616, 2014). "In the course of the HIV-1 infection, however, the contribution of DCs to the antiviral state could be confounded by their ability to facilitate HIV-1 transmission to bystander CD4+ T cells and promote viral spread." (PMID 25033082, 2014). "We first tested whether common gamma chain cytokines alter CD62L expression on resting naïve and memory peripheral blood CD4 T cells, finding that each maintained high CD62L expression at concentrations which enhance HIV-1 infection." (PMID 25330112, 2014). "A cohort study of patients with primary, chronic and long-term non-progressive HIV-1 infection showed that CD127 down regulation on CD4 T-cells was rapidly reversible and returned to normal levels less than 24 hours after incubation ex vivo in fresh medium." (PMID 25333710, 2014). "We demonstrated that exosomes released by CD4+ T cells, but not CD4− T cells, efficiently inhibit HIV-1 infection in vitro." (PMID 25423108, 2014). "Most importantly, our results showed that exosomes released by CD4+ T cells expressing Nef were not able to efficiently reduce HIV-1 infection, probably due to the decreased expression of CD4 in these exosomes." (PMID 25423108, 2014). "Most surprisingly, depletion of pDC during chronic HIV-1 infection rescued human leukocytes including human CD4 T cells in lymphoid organs but not in blood, in spite of higher levels of HIV-1 replication." (PMID 25077616, 2014). "HIV-1 infection is a chronic infection with non-stop viral replication leading to a decrease in the number of T CD4 lymphocytes and immunosuppression." (PMID 24964202, 2014). "Thus, exosomes were added to unstimulated CD4+ T lymphocytes either: i) six hours before infection with the T-tropic NL4-3 HIV-1 strain; ii) together with HIV-1, and iii) six hours after HIV-1 infection." (PMID 24924541, 2014). "Cathepsin G, a neutrophil-derived serine protease that is present in human CVF, has been reported to bind the HIV-1 envelope protein gp120, and can promote HIV-1 infection of macrophages, but not CD4+ T lymphocytes." (PMID 27025760, 2014). "With most of the pseudoviruses, Cc-CD4M33F23 was more effective than Cc-CD4 in preventing HIV-1 infection, but the difference between these two constructs was not statistically significant." (PMID 23840383, 2013). "LTNP within the Chelsea and Westminster HIV cohort are defined by a duration of HIV-1 infection longer than 7 years from time of HIV-1+ diagnosis, in the absence of cART and clinical symptoms, and the stable maintenance of CD4+ T-cell count within the normal reference range." (PMID 23459797, 2013).
HIV-1 infection (continued). "A recent study confirmed the central role of IFNα in HIV-1 infection by showing that IFNα is the dominant type I IFN detectable in the plasma of HIV-infected individuals and that its levels correlate with immune activation and depletion of CD4+ T cells." (PMID 24133492, 2013). "Previous studies using PBMCs or CD4+ T cells from infected viremic, elite controllers and multiply exposed uninfected (MEU) subjects indicate that HIV-1 infection and/or virus exposure resulted in signature miRNA expression profile further supports the role of HIV-1 induced miRNA regulation." (PMID 23721325, 2013). "Although galectin-9/TIM-3 interaction was reported to protect human CD4 T cells against HIV-1 infection, to date there are no reports demonstrating a specific binding of human galectin-9 to human TIM-3." (PMID 23555261, 2013). "Frequencies of LAP+ CD4 Treg were not significantly reduced in HIV-1 infection, and unrelated to immune activation." (PMID 23382678, 2013). "In LTNP, and other patients exhibiting stable CD4 T-cell counts throughout HIV-1 infection, the thymic epithelium, as with peripheral CD4+ T cells, may be resistant to HIV-1 infection." (PMID 23459797, 2013). "Clinical evaluation of immune reconstitution and health status during HIV-1 infection and anti-retroviral therapy (ART) is largely based on CD4+ T cell counts and viral load, measures that provide a somewhat incomplete picture of the true functional status of the immune system." (PMID 23717651, 2013). "In summary, we demonstrated for the first time that one of the major roles of Vpr in HIV-1 infection and pathogenesis is to enhance R5 HIV-1 propagation by exploiting proliferating CCR5+ CD4+ T cells including Tregs during acute infection, which can subsequently induce immune activation." (PMID 24339781, 2013). "We provide evidence that lack of HIV-specific CD4 helper responses and high PD-1 expression in the setting of HIV-1 infection both contribute to B cell dysfunction." (PMID 24358343, 2013). "SAMHD1 activity is not correlated with its expression levels, as only resting CD4 T cells restrict HIV-1 infection." (PMID 24167505, 2013). "Although the system of cervico-vaginal and lymphoid tissue ex vivo seems to adequately simulate the main hallmarks of HIV-1 infection, such as the size of the pool of HIV-1 infected CD4+ T cells, the depletion of CD4+ T cells by HIV-1, etc., it has limitations." (PMID 23408885, 2013). "GLUT1 is a receptor of HTLV infection in CD4+T cells, and HIV-1 infection in CD4+T cells is abrogated in the absence of surface GLUT1." (PMID 23724114, 2013). "Recent studies suggest that the induction of HIV-1-specific CD4+ T helper cells and polyfunctional CD8+ T cells could play an important role in controlling HIV-1 replication and spread in patients with HIV-1 infection." (PMID 23516578, 2013). "Are CD4 T-Cells from LTNP and EC Resistant to HIV-1 Infection?" (PMID 23630526, 2013). "We have consistently found that there is a transient, greatly increased rate of activation and proliferation of CD4 T-cells which results in high levels of CD38high, CCR5+, Ki67+, and CD127low cells, making ideal targets for highly productive HIV-1 infection." (PMID 23630526, 2013). "This indicates that classical Treg decline at a slower rate than conventional CD4 T cells during progressive HIV-1 infection, and suggests that these cells may play an important role in the immune pathogenesis of HIV-1 infection." (PMID 23382678, 2013). "Primary HIV-1 infection is a period when a vigorous immune response to HIV-1 antigens occurs, with appearance of antibodies, as well as a dramatic increase in activated CD4 and CD8 T-cells." (PMID 23630526, 2013).
HIV-1 infection (continued). "Clinical evaluation of immune reconstitution and health status during HIV-1 infection and anti-retroviral therapy (ART) is largely based on CD4+ T cell counts and viral load, measures that fail to take into account the CD8+ T cell subset, known to show features of accelerated aging in HIV disease." (PMID 23717651, 2013). "The genetic similarity of HIV-1 DNA populations in CD4+ T-cells from lymph node tissue, peripheral blood and HIV-1 RNA from plasma implies ongoing exchange of virus and/or infected cells between these compartments during untreated chronic HIV-1 infection." (PMID 23818847, 2013). "Altogether there is not clear-cut evidence that EC have CD4 T-cells that are resistant to HIV-1 infection." (PMID 23630526, 2013). "Conventional CD25hi CD4 Treg express HIV-1 co-receptors and are targets for HIV-1 infection." (PMID 23382678, 2013). "It is conceivable that SAMHD1-restriced HIV-1 infection in DCs would limit viral spreading from DCs to CD4+ T-cells, although the experimental evidence is lacking." (PMID 24523981, 2013). "HIV-1 infection is characterized by T cell activation, inflammation, and hyper-coagulation, yet, effects of antiretroviral therapy (ART) on dynamics of these indices and correlates of CD4+ T cell reconstitution are incompletely understood." (PMID 24367599, 2013). "Purified CD4 cells derived from rectal biopsies in macaques indicate identical TFV-DP levels when compared to PBMC levels, which suggests that the PBMC surrogate marker is a good indicator for TFV-DP levels in cells relevant to HIV-1 infection." (PMID 22808148, 2012). "Given that CD4+ T cells are the main targets for HIV-1 infection and replication in vivo, it is critical to evaluate whether cocaine enhances HIV-1 replication in primary CD4+ T cells." (PMID 23251514, 2012). "In summary, we observed significantly lower levels of LEDGF/p75 in CD4+ lymphocytes of HESN subjects, suggesting that LEDGF/p75 may play a role in the in vivo resistance to HIV-1 infection." (PMID 22479480, 2012). "F-actin is required for CD4 and CXCR4 redistribution, and it has been shown that activated moesin promotes F-actin redistribution and CD4-CXCR4 clustering, which are required for efficient X4-tropic HIV-1 infection in permissive lymphocytes." (PMID 23251513, 2012). "These CD4+ T cells are reminiscent of CD8+ T cells that exhibit non-cytotoxic responses that suppress HIV-1 infection." (PMID 23346088, 2012). "The phenotypes of these resting T cells carrying a nonproductive HIV-1 infection have specific set of surface markers such as CD4+, CD25−, CD69−, and HLA-DR−." (PMID 22548060, 2012). "Although soluble CD4 (sCD4) can inactivate laboratory-adapted HIV-1 strains, it fails to reduce the viral loads in clinical trials because of its low potency against primary isolates and tendency to enhance HIV-1 infection at low concentration." (PMID 23217195, 2012). "HHV-6 and human herpesvirus 7 (HHV-7), that have infection rates of 100% each in the human population, infect, similar to HIV, CD4+ T-cells, and could thus (partly) be responsible for HERV induction seen in PBMC's after HIV-1 infection." (PMID 22248111, 2012). "Thus, it is important to analyze expression levels and the activity of ribonucleotide reductases in resting and activated CD4+ T-cells to further understand the mechanisms by which SAMHD1 regulates the dNTP pool and HIV-1 infection efficiency in these cells." (PMID 23092163, 2012). "In the chronic phase of HIV-1 infection, IP-10 showed a strong positive correlation with VL and a negative one with CD4+ T cell counts." (PMID 23056251, 2012). "Although coreceptor signaling is not essential for HIV-1 infection, several recent studies have suggested that chemokine receptor signaling enhances infection of resting CD4+ T cells." (PMID 22448282, 2012). "It is known that activated CD4 T cells preferentially support productive HIV-1 infection and that HIV-1 infection may activate bystander cells." (PMID 23236398, 2012).